CBR4 (carbonyl reductase 4)
Description:
Component of the heterotetramer complex KAR (3-ketoacyl-[acyl carrier protein] reductase or 3-ketoacyl-[ACP] reductase) that forms part of the mitochondrial fatty acid synthase (mtFAS). Beta-subunit of the KAR heterotetramer complex, responsible for the 3-ketoacyl-ACP reductase activity of the mtFAS, reduces 3-oxoacyl-[ACP] to (3R)- hydroxyacyl-[ACP] in a NADPH-dependent manner with no chain length preference, thereby participating in mitochondrial fatty acid biosynthesis. The homotetramer has NADPH-dependent quinone reductase activity (in vitro), hence could play a role in protection against cytotoxicity of exogenous quinones. As a heterotetramer, it can also reduce 9,10-phenanthrenequinone, 1,4-benzoquinone and various other o-quinones and p-quinones (in vitro).
Synonyms: SDR45C1; FLJ14431
Tractability: Small molecule: a structure with a bound ligand is known. PROTAC: ubiquitination databases record sites on it; its protein half-life has been measured.
Gene: Protein-coding gene on chromosome 4 (168,863,770 to 169,010,311, reverse strand). Ensembl gene ENSG00000145439.
Subcellular location: Mitochondrion matrix
Pathways (Reactome):
Metabolism: Fatty acyl-CoA biosynthesis
Gene Ontology:
Molecular function: 3-oxoacyl-[acyl-carrier-protein] reductase (NADPH) activity; NAD(P)H dehydrogenase (quinone) activity; NADPH binding; NADPH dehydrogenase (quinone) activity; protein binding; quinone binding; oxidoreductase activity, acting on the CH-OH group of donors, NAD or NADP as acceptor
Biological process: daunorubicin metabolic process; doxorubicin metabolic process; fatty acid biosynthetic process; protein heterotetramerization; protein homotetramerization; fatty-acyl-CoA biosynthetic process; lipid metabolic process
Cellular component: mitochondrial matrix; mitochondrion; oxidoreductase complex
Genetic constraint (gnomAD): Loss-of-function variants: 18 observed, 14.37 expected, observed/expected ratio (o/e) 1.25, 90% interval 0.86 to 1.79. The upper end of that interval is the gene's LOEUF score, 1.79, which puts it in group 6 of 6, group 1 being the genes least tolerant of losing a copy. Missense variants: 203 observed, 201.84 expected, observed/expected ratio (o/e) 1.01, 90% interval 0.9 to 1.13. Synonymous variants: 74 observed, 77.37 expected, observed/expected ratio (o/e) 0.96, 90% interval 0.79 to 1.16.
Homologues: Orthologues: chimpanzee CBR4 (99% identical), macaque CBR4 (97% identical), dog CBR4 (92% identical), rabbit CBR4 (92% identical), guinea pig CBR4 (91% identical), mouse Cbr4 (86% identical), pig CBR4 (85% identical), rat Cbr4 (76% identical), tropical clawed frog cbr4 (66% identical), zebrafish cbr4 (65% identical), Drosophila melanogaster Adhr (25% identical).
Diseases named in the same sentence as CBR4 in open-access papers:
CBR4 is named in the same sentence as 8 diseases in open-access papers, as found by Europe PMC text mining. Sharing a sentence is not in itself a finding about the gene and the disease. The quoted sentences say what the papers report.
amyotrophic lateral sclerosis (1 paper, 2024). Amyotrophic lateral sclerosis (ALS) is a neurodegenerative disease characterized by progressive muscular paralysis reflecting degeneration of motor neurons in the primary motor cortex, corticospinal tracts, brainstem and spinal cord. "A more comprehensive analysis indicates that upregulated proteins (ELOVL5, ELOVL7, TECR, HSD17B4, ACSL1, HACD2, and CBR4) are significantly enriched within the pathways of oxidative phosphorylation and metabolic pathways pertinent to amyotrophic lateral sclerosis." (PMID 39335340, 2024).
tumor (3 papers, 2021 to 2025). "Conversely, QGP‐1 cells with stable CBR4 over‐expression decelerated tumor growth compared with the control group." (PMID 39524139, 2024). "And Ki67 expression levels were obviously lower in CBR4 over‐expression tumors while higher in CBR4 knockdown tumors, which further proved that CBR4 is a tumor suppressor." (PMID 39524139, 2024). "We examined the roles of CBR4 in vivo by building tumor xenograft models.The QGP‐1 cells respectively transfected with CBR4 knockdown,CBR4 over‐expression vector and control vector were implanted in nude mice." (PMID 39524139, 2024). "Overall, our results uncovers the CBR4/FASN/mTOR axis as a mechanism for tumor development and inspires us a new molecular guide for the therapeutic strategies for GEP‐NETs treatment." (PMID 39524139, 2024). "And further results prove the anti‐tumor status of CBR4 in the GEP‐NETs by decreasing the expression of FASN in an ubiquitin proteasome manner, which might provide a new inspiration for treatment." (PMID 39524139, 2024). "And immunofluorescence showed the location of CBR4 and FASN in GEP‐NETs cell lines, and lower levels in tumor cells than normal cells." (PMID 39524139, 2024). "Furthermore, we found that orlistat might reverse the tumor suppression effect of CBR4." (PMID 39524139, 2024). "To ascertain whether CBR4 plays a tumor suppressor role in GEP‐NETs, we generated stable CBR4 over‐expressing QGP‐1 and STC‐1 cell lines via stable transfection." (PMID 39524139, 2024).
cancer (2 papers, 2022 to 2024). A tumor composed of atypical neoplastic, often pleomorphic cells that invade other tissues. "In our application, orlistat was found to inhibit cell proliferation, migration and invasion by specifically inhibiting FASN on CBR4 knockdown cells, and reversed the cancer‐promoting effect of FASN." (PMID 39524139, 2024). "However, the role of the top three genes (MMAA, SUCLG2 and CBR4) negatively correlated with POLD1 expression in cancers is not elucidated." (PMID 35189839, 2022).
CBR4 also shares sentences with these, for which no sentence is quoted: breast carcinoma (1 paper); energy metabolism disorder (1); infection (1); metabolic disorders (1); neuroendocrine tumors (1).